GAB1 (GRB2 associated binding protein 1)
Diseases named in the same sentence as GAB1 in open-access papers (continued):
Sharing a sentence is not in itself a finding about the gene and the disease.
urothelial carcinoma (1 paper, 2015). A malignant neoplasm derived from the transitional epithelium of the urinary tract (urinary bladder, ureter, urethra, or renal pelvis). "Taken together, our results highlight the unique role of Gab1 in the regulation of mTORCs after EGF stimulation as well as the crucial role of Gab1 in urothelial carcinoma." (PMID 25596749, 2015). "Taken together, our results indicate that both Gab1 and mTORCs are important in urothelial carcinoma." (PMID 25596749, 2015). "Based on in vivo and in vitro studies, we have identified increased expression of Gab1 and phosphorylation of mTORCs in rats with urothelial carcinoma and human urothelial carcinoma tumor tissues." (PMID 25596749, 2015). "Here, we examined the expression of Gab1 in many cells lines from different grades of urothelial carcinoma." (PMID 25596749, 2015). "Compared to normal bladder tissue, the expression of Gab1 and activity of mTORCs are elevated in urothelial carcinoma." (PMID 25596749, 2015). "In this study, we used urothelial carcinoma cells to demonstrate that Gab1 was important for mTORC activation." (PMID 25596749, 2015). "We believe that Gab1 may be a biomarker to predict the diagnosis and drugs response of urothelial carcinoma." (PMID 25596749, 2015). "Therefore, Gab1 may play an important role in regulating EGF-mediated mTORC activity in urothelial carcinoma." (PMID 25596749, 2015). "Indeed, the expression level of Gab1 was found to be weaker in normal urothelial cell lines (E6, normal) and low-grade urothelial carcinoma cell lines (RT4, Grade I; TSGH8301, Grade II) and higher in high-grade urothelial carcinoma cell lines (J82, T24, Grade III)." (PMID 25596749, 2015). "In the present study, the critical role for Gab1 in EGF-mediated activation of mTORC pathways and the importance of Gab1 and mTORCs in urothelial carcinoma were investigated." (PMID 25596749, 2015). "Collectively, our results suggest that Gab1 is an essential regulator of the EGF-mediated mTORC pathways and may potentially be used as a biomarker for urothelial carcinoma to predict diagnosis and drug response." (PMID 25596749, 2015).
tumor (42 papers, 2013 to 2026). "All these functions of GAB1 appear to be fundamental to the processes underlying malignant transformation, including tumor angiogenesis and metastasis." (PMID 37627207, 2023). "GAB1 expression is altered in a wide variety of tumors and is associated with poor patient prognosis in several tumor types." (PMID 37627207, 2023). "Taken together, these results indicate that expression of Gab1 is not only upregulated in BCa patients with malignant tumor growth and a poor prognosis but also positively associated with tumor metastasis." (PMID 30665442, 2019). "Scale Bar: 50 μm (e) Expression of Gab1 is positively associated with tumor progression by data analysis from Oncomine database." (PMID 30665442, 2019). "GAB1 expression is increased and strongly associated with tumor progression and prognosis in patients with HCC." (PMID 26871477, 2016). "More importantly, the combined GRB2 and GAB1 protein expression was significantly associated with aggressive tumor progression and poor prognosis in patients with HCC." (PMID 24391994, 2013). "Moreover, the combined GRB2 and GAB1 protein expression was significantly associated with aggressive tumor progression and poor prognosis in patients with HCC." (PMID 26204832, 2015). "Next, we measured the expression of GAB1 fromxenograft tumor tissues including si-AK001796#1 groups and NC groups, we foundthat GAB1 was reduced in vivo (P=0.0019)." (PMID 37272834, 2023). "Tumors engrafted in GAB1-ecKO mice have been shown to have a substantially lower level of capillary density, as well as a marked decrease in tumor weight and volume." (PMID 37627207, 2023). "In AXL-low-expressing tumor cells, EGFR and IGF-1R bind constitutively and to each protein associated with their adaptor proteins, including Gab1." (PMID 32929081, 2020). "(a) Protein expression of Gab1 is increased in 6 of 8 BCa tissues when compared to the adjacent normal tissues (N: normal tissues, T: tumor tissues)." (PMID 30665442, 2019). "We report that miR-150 expression is downregulated in HCC tissues and acts as a tumor suppressor by inhibiting the GAB1-ERK axis in HCC." (PMID 26871477, 2016). "GRB2 positive staining was localized in the cell nucleus and cytoplasm, while GAB1 positive staining was localized in the cytoplasm of tumor cells in HCC tissues." (PMID 24391994, 2013). "GAB1 overexpression was also observed more frequently in HCC tissues with high tumor grade than those with low grade (P=0.02)." (PMID 24391994, 2013). "Studies have found that Gab1 up-regulates proto-oncogene expression via participation in amplification of signaling pathways related to tumor biological behaviors and plays a role in the occurrence and development of tumors." (PMID 24312291, 2013). "More importantly, the combined GRB2 and GAB1 protein expression was significantly associated with serum AFP (P=0.01), tumor stage (P=0.006) and tumor grade (P=0.02)." (PMID 24391994, 2013). "Consequently, key proteins involved in tumor progression and metastasis, including p-Akt, p-Gab1, and FOXO1, were markedly inhibited in tumors from CDP-treated mice." (PMID 41683520, 2026). "Moreover, aggressive tumor progression and poor prognosis in patients with HCC are closely associated with a significant increase in Gab1 expression." (PMID 38935609, 2024). "Furthermore, IL-6 induces the association of GAB1 with SHP2 and CRKL in these tumor cells, promoting cell proliferation." (PMID 37627207, 2023). "However, further pre-clinical studies and clinical trials are needed for the clinical application of GAB1 inhibitors in specific tumor contexts." (PMID 37627207, 2023). "Furthermore,a remarkable relationship between GAB1 level and miR-150 level was observed in60 tumor samples from TCGA database (r = −0.2707, P < 0.001)." (PMID 37272834, 2023). "In addition, genetic rearrangements involving GAB1 have been described in different pediatric and adult tumor contexts." (PMID 37627207, 2023).
tumor (continued). "This study provides a solid basis for investigating the role of GAB1 in the tumor microenvironment." (PMID 37627207, 2023). "Considering the GAB1 involvement in the different hallmarks of cancer, this protein could be a potential therapeutic target to treat different tumor types." (PMID 37627207, 2023). "Overall, circDHTKD1 could sponge miR-326 to upregulate GAB1 expression to promote tumor growth and metastasis in OSCC." (PMID 34287578, 2021). "However, Mouradian and other scientists found that linoleic acid increases the activity of PI3K/AKT signaling pathway, promotes the proliferation of LC cells, and leads to tumor formation, with GAB1 as the main target of linoleic acid." (PMID 33643040, 2020). "In addition, a recent bioinformatic study indicated that a structure-based approach to target the pleckstrin homology (PH) domain of Gab1 represents a potential tumor-specific cytotoxicity against MDA-MB-231 and T47D BCa cell lines in vitro." (PMID 30665442, 2019). "To investigate whether this pathway participates in regulating tumor cell invasion, we selected Gab1 siRNA and VEGFR-2 siRNA with the highest interference efficiency to transfect into ICBD-1 cells." (PMID 24312291, 2013). "In addition, the frequencies of aberrant GAB1 expression were higher in HCC tissues with higher tumor stage (T3~4) than those with lower tumor stage (P=0.01)." (PMID 24391994, 2013). "Further experimental validation indicated that the aberrant expression of GRB2 and GAB1 proteins may be strongly related to tumor progression and prognosis in patients with HCC." (PMID 24391994, 2013). "We presumed that Gab1 might affect the biological behaviors of tumor cells by mediating VEGFR-2 via PI3K/Akt and could influence the invasion and metastasis of tumor cells via MMP-9." (PMID 24312291, 2013). "Additionally, the downregulated fibroblast growth factor receptors 3 and 4, PDGFA, and GAB1 (GRB2-associated binding protein 1), which take part in FGF signaling, indicate downregulation of this pathway and possible suppression of tumor cell invasiveness and EMT." (PMID 37834191, 2023). "However, further studies on the role of GAB1 in tumor angiogenesis are needed." (PMID 37627207, 2023). "The low miR-409 expression may accelerate the tumor cell progression of PC by targeting GAB1." (PMID 34338153, 2021). "Upregulation of miR-409 may suppress tumor cellular behaviors by targeting GAB1." (PMID 34338153, 2021). "Moreover, SHC1 was downregulated by miR-5582-5p, thus led a tumor suppressive activity with GAB1." (PMID 33936170, 2021). "Further investigation, such as employing a spontaneous mammary carcinogenesis and tumor metastasis transgenic mouse model for phenotype observation and mechanism exploration, is still required to be carried out for potential application of Gab1 in diagnosis and therapy of metastatic BCa." (PMID 30665442, 2019). "Interestingly, the coexpression of GRB2 and GAB1 may be associated with serum AFP, tumor stage, tumor grade and patient prognosis." (PMID 24391994, 2013). "Forced expression of GAB1 or Myr-GAB1 significantly promoted the tumor growth, with average tumor volumes reaching 300 mm3, 825 mm3, or 1655 mm3 at the end of experiment for SUNE-1-V, SUNE-1-GAB1 or SUNE-1-Myr-GAB1 xenografts respectively." (PMID 40533463, 2025). "In our attempts to identify the potential cell signalling pathway, we noticed that ROK/Gab-1 and PI3K/AKT are the two main pathways for cell proliferation and differentiation, which have been reported for tumour cells and stem cells." (PMID 37707669, 2023). "We found that TGFA, SHC1, PIK3CD, GAB1, and AKT3 were negatively correlated with six tumor immune cells in KIRC, and EIF4EBP1 was positively correlated with macrophage infiltration." (PMID 35903358, 2022). "Besides, miR-409 could function as a tumor suppressor in several cancers by targeting zinc-finger E-box-binding homeobox-1 (ZEB1), E74-like factor 2 (ELF2), and GRB2-associated binding protein 1 (GAB1)." (PMID 34338153, 2021).
tumor (continued). "In conclusion, circDHTKD1 increased the expression of GAB1 by sponging miR-326 in OSCC, inducing the promotion of tumor growth and metastasis in vitro and in vivo." (PMID 34287578, 2021). "Genes such as IL6, GAB1, and VANGL1, were upregulated both in the tumor buds and in the microenvironment." (PMID 28687755, 2017). "As GAB1 is a target gene of miR-150, miR-150 overexpression inhibits the function of GAB1 to suppress epithelial-mesenchymal transition (EMT) in tumor cells." (PMID 29296185, 2017). "Knockdown of GAB1 mimicked the tumor-suppressive effects of miR-150 overexpression on HCC cells, whereas restoration of GAB1 expression partially abolished the inhibitory effects." (PMID 26871477, 2016). "GAB1 upregulation promotes tumor cell invasion, migration via CXCR4 and tumor growth." (PMID 31024232, 2019). "(f) Overexpression or knockdown of Gab1 does not display a significant influence on tumor growth in vivo by subcutaneous xenograft models." (PMID 30665442, 2019). "Two methods–immunofluorescence and immunoblotting–were used for the detection of four molecular markers (β-catenin, filamin A, GAB1 and YAP1) in patient-derived cell lines to compare the results with those obtained from the corresponding tumor samples on the protein level." (PMID 28231263, 2017). "The results of the present study demonstrated that the D61G mutant, a known GOF mutant of SHP2, enhanced the interaction between Gab1 and SHP2 and increased activation of the MAPK-PI3K pathway, which in turn promoted tumour migration and invasion and other malignant behaviours." (PMID 26673822, 2016). "Activation of both c-Met/Gab1/FAK and c-Met/Gab1/PAK signalings promotes tumor metastasis." (PMID 25971889, 2015). "Notably, negative correlations between GAB1 and Smurf1 or Smurf2 were observed, confirming the downregulated expression of Smurf1 and Smurf2 in Shh-MB and supporting a tumor-suppressive role of Smurf1 and Smurf2 during Shh-MB progression." (PMID 37537194, 2023). "Since HGF activated MET/GAB1 pathway in entrectinib‐treated HCC78 cells, the timing of tumor cell lysate harvesting might not be optimal for detecting HGF‐induced MET phosphorylation." (PMID 36416133, 2023).
cancer (38 papers, 2012 to 2025). A tumor composed of atypical neoplastic, often pleomorphic cells that invade other tissues. "Embryonic development is disrupted in GAB1-deficient mice, and oncogenic mutations have been noted in cancer cases." (PMID 37627207, 2023). "The over-expression of Grb2-associated binding protein 1 (GAB1) occurs in numerous cancers, thus drugs designed to inhibit the activity of GAB1 are studied, including drugs that target the PH domain." (PMID 34681286, 2021). "Studies have implied Gab1 as a oncogenic protein in multiple human cancers, whose overexpression is associated with cancer cell progression." (PMID 28291820, 2017). "GAB1 plays a role in tumorigenesis by involving in c-Met receptor signaling, since c-Met is activated, mutated, or overexpressed in a wide range of cancers." (PMID 24391994, 2013). "This review focuses on GAB1’s influence on cellular transformation particularly in proliferation, evasion of apoptosis, metastasis, and angiogenesis—each of these processes being a cancer hallmark." (PMID 37627207, 2023). "In this paper, we described the identification and evaluation of a set of first-in-class potent inhibitors targeting a new cancer target, Grb2-associated binder-1 (GAB1), which integrates signals from different signaling pathways, and is frequently over-expressed in cancer cells." (PMID 25569504, 2015). "Imbalance of Gab1 activity plays an important role in cancer progression and metastasis in a wide range of tumors." (PMID 38935609, 2024). "GAB1 expression levels are disrupted in various tumors, and elevated levels in patients often portend a worse prognosis in multiple cancer types." (PMID 37627207, 2023). "Coupled with the fact that Gab1 is frequently overexpressed in human cancers, it’s central role in multiple signaling pathways has made Gab1 an attractive candidate for therapeutic drug discovery." (PMID 35083168, 2021). "Elevated expression of GAB1 has been observed in human cancers, and downregulation of GAB1 by cellular miRNAs has been shown to reduce proliferation in normal and transformed cell types (77, –, 83)." (PMID 32759334, 2020). "GAB1 is a critical protein in cellular signaling, and its PH domain has been suggested as an attractive target for various cancer treatments." (PMID 25569504, 2015). "The Grb2-associated binding protein 1 (GAB1) integrates signals from different signaling pathways and is over-expressed in many cancers, therefore representing a new therapeutic target." (PMID 25569504, 2015). "In the present study, we aim to target the pleckstrin homology (PH) domain of GAB1 for cancer treatment." (PMID 25569504, 2015). "In the present work, we utilized several inhibitors to investigate the dynamics of GAB1 PH domain and evaluate their selectivity in potential cancer cell inhibition." (PMID 25569504, 2015). "Herein, we attempt to identify novel small molecule inhibitors selectively targeting the PH domain of GAB1 and suggest that these small molecules exhibit high therapeutic potency for cancer treatment." (PMID 25569504, 2015). "Gab1 plays a critical role in fibrogenesis and tumorigenesis in various cancers, including HCC." (PMID 38935609, 2024). "Gab1 expression is elevated in various cancers and is involved in carcinogenesis and metastasis." (PMID 38935609, 2024). "Studies reveal that GAB1 significantly influences cellular transformation by changes in proliferation, evasion of apoptosis, metastasis, and angiogenesis—all fundamental processes in cancer development." (PMID 37627207, 2023). "GAB1 acts as a signal integrator of multiple signaling pathways and is deregulated in many cancers." (PMID 37627207, 2023). "In numerous types of cancer, high GAB1 expression levels correlate with a poor prognosis." (PMID 37627207, 2023).